ENSG00000279284 ( gene)
Diseases named in the same sentence as ENSG00000279284 in open-access papers (continued):
Sharing a sentence is not in itself a finding about the gene and the disease.
tumor (continued). "In this study, we showed that GSK3β acts as a tumour suppressor gene; m6A‐modifed GSK3β was recognized and degraded by YTHDF2, leading to the activation of Wnt/β‐catenin signalling and further promoting the proliferation of CRC cells in vitro and in vivo." (PMID 34709763, 2021). "miR-149 is abnormally expressed in several malignant tumors and can be used as an oncogene or tumor suppressor gene to regulate the biological behavior of tumor cells." (PMID 34957298, 2021). "MALAT1 is highly expressed in PTC, as an oncogene to promote tumor EMT, and as a tumor suppressor gene to inhibit tumorigenesis in poorly differentiated and anaplastic thyroid carcinoma." (PMID 34930256, 2021). "In lymphoid tissues far away from tumor cell areas expression of the immune-related gene CD74 was observed while in tissues in close proximity to tumor cell areas, expression of the immune-related gene IGLL5 was seen." (PMID 35008286, 2021). "miR-182-5p as a gene with complicated functions can serve as an oncogene or a tumor suppressor gene in different cancers." (PMID 33959160, 2021). "Since MLL3 acts as a tumor-suppressive gene in multiple cancer types, we examined its function on TNS3 in several cancer cell lines, including U2OS, HeLa, 769-P, and MDA-MB-231." (PMID 33824309, 2021). "Somatic copy-number alterations (SCNAs) affect a larger fraction of the genome, which can potentially activate an oncogene or inactivate a tumor suppressor gene." (PMID 34945000, 2021). "PRICKLE1 has been reported to be a negative regulator of the Wnt/beta-catenin signaling pathway and is a putative tumor suppressor gene in HCC." (PMID 34660596, 2021). "Collectively, these findings are consistent with the notion that KrasWT acts as a relative tumor-suppressor gene in the presence of oncogenic Kras and that its deletion leads to the hyperactivation of the Kras pathway." (PMID 34172714, 2021). "A previous study indicated that miR-137 plays a role as a tumour suppressor gene in multiple tumours." (PMID 33413360, 2021). "For instance, H19 can exhibit proto‐oncogene activities that promote tumour development and growth, but can act as a tumour suppressor gene in other tumours by inhibiting tumour proliferation, metastasis and invasion." (PMID 33236528, 2021). "FOXJ1 is hypermethylated in BRCA cell lines and clinical tissue samples, revealing its role as a putative tumor suppressor gene." (PMID 33688372, 2021). "We found that PJVK was downregulated in tumour tissues, and its low expression predicted poor survival rates, indicating that it functioned as a tumour suppressor gene in this study." (PMID 33828074, 2021). "Altogether, these studies suggested that LINC01296 can present different expression levels in different tumor types, both as an oncogene or a tumor suppressor gene." (PMID 34515611, 2021). "The suppressor of cytokine signaling 1 (SOCS1) is a tumor-suppressor gene and suppresses cytokine signaling and destroys the HPV E7 protein." (PMID 35096000, 2021). "Programmed cell death 4 (PDCD4) is a proinflammatory tumor-suppressor gene which helps to prevent the transition from chronic inflammation to cancer." (PMID 33288677, 2021). "In conclusion, our study suggested that miR-513b-5p inhibited the expression of TRIB1 and exerted a tumor suppressor gene in Weri-RB1 cells." (PMID 34589612, 2021). "A discrepancy of the result is that FBXW7 is a cancer suppressor gene and there are proofs that mutation of FBXW7 can increase the degree of malignancy of tumor cells." (PMID 35712679, 2021). "Meanwhile, miR-98-5p has been reported as a tumor suppressor gene to inhibit tumor growth and metastasis in a variety of cancers, and associated with resistance to anti-tumor drug therapy." (PMID 34837929, 2021).
tumor (continued). "Recently, the anti-tumor effect of LHPP has been further demonstrated: LHPP is considered as a tumor suppressor gene of hepatocellular carcinoma by the PI3K/AKT signaling pathway, and its low expression leads to a decrease in patient survival rate." (PMID 32186702, 2020). "Several investigations demonstrated that lncRNA GAS5 can act as a tumor suppressor gene by different actions." (PMID 32727450, 2020). "It has been reported that the CTCC-binding protein (CTCF) acts as a tumor suppressor gene by regulating the expression of tumor-related genes." (PMID 33256112, 2020). "Our previous studies showed that promoter methylation caused Upf1 downregulation in HCC and that Upf1 regulated hepatocarcinogenesis and acted as a tumor suppressor gene in HCC." (PMID 32802196, 2020). "Ras association domain family 1A (RASSF1A), a well-recognized tumor suppressive gene in various types of tumors, is a putative tumor suppressor gene located on the 3p21.3 locus 38-40." (PMID 33193895, 2020). "In the present study, miR-192 was demonstrated to show low expression in OSA tissues and cells, supporting that miR-192 served as a tumor suppressor gene in OSA, which is consistent with the previous study." (PMID 33097010, 2020). "PDCD4, one of the targets of miR-21, was demonstrated to be a tumor-suppressor gene and the target of procancer miRNAs (Lankat-Buttgereit and Göke, 2009)." (PMID 33329700, 2020). "Lumican has two opposite effects on the occurrence and the development of tumors as it can act as an oncogene or a tumor suppressor gene." (PMID 32500021, 2020). "Several studies have suggested that SEPT9 acts a tumor suppressor gene and plays an important role in the regulation of cell division during its hypermethylation in liver carcinogenesis." (PMID 33178361, 2020). "Our results showed that miRNA‐96‐5p is an miRNA that functions as an oncogene, and FOXO3 is a tumor suppressor gene." (PMID 32100957, 2020). "As one of the least studied sirtuin family members, the mitochondrial sirtuin SIRT4 is a tumor suppressor gene in various cancers." (PMID 32863939, 2020). "A previous study reported that methylation of CCNA1, a tumor suppressor gene, can differentiate between low and high grade lesions." (PMID 32102526, 2020). "In some studies, low expression of lncRNA in cancer tissues has been found to act as a tumor suppressor gene and inhibit tumor progression." (PMID 33174687, 2020). "On the other hand, miR-552 targets PTEN, a key tumor suppressive gene, and thus promotes OC growth and metastasis." (PMID 32984052, 2020). "In this study, we found that miR-330-5p was downregulated in BC and functioned as a tumor-suppressor gene in BC." (PMID 33176280, 2020). "Several studies have reported that miRNA-204 expression is downregulated in tumor tissues than in normal tissues, and it is thus generally regarded to be a tumor suppressor gene." (PMID 32158466, 2020). "CpG island methylator phenotype (CIMP) can result in the silencing of key genes important for tumor progression, including the tumor‐suppressor gene, CDKN2A, and the DNA mismatch repair gene, MLH1." (PMID 33005848, 2020). "Recent studies also revealed that TIPE1 probably serves as a tumor suppressor gene in several tumor types." (PMID 33520705, 2020). "Adenine-thymine (AT)–rich interactive domain-containing protein 1a (ARID1a) is a tumor suppressor gene." (PMID 30811493, 2019). "Earlier studies also prove SNHG20 as tumor-suppressive gene in other tumors consistent with our findings." (PMID 30744670, 2019). "Chmp1A and CADM2, belonging to cell adhesion molecules family, had been found to be a tumor suppressor gene in RCC." (PMID 32038722, 2019).
tumor (continued). "Based on above results, we considered that the NLRP3 was tumor suppressor gene in ccRCC and the NLRP3 inflammasome is an important functional effector of LXRα in ccRCC cells for the first time." (PMID 30770793, 2019). "All the data indicated that LINC00982 acts as a tumor suppressor gene, and revealed LINC00982-PI3K/AKT signaling pathway regulatory network contributes to PTC." (PMID 31262968, 2019). "To conclude, we show that PDCD4, a tumor suppressor gene suppressed in many cancers, is regulated through a relationship between miR-21 and miR-499." (PMID 31235478, 2019). "TCF12, which is known to be involved in the regulation of cell growth and differentiation, has been reported to function as an oncogene or a tumor suppressor gene in the progression of various malignant tumors." (PMID 31534521, 2019). "Particularly, TSLC1 (CADM1; cell adhesion molecule 1) located in 11q23.3 has an important role as tumor suppressor gene in NB and has also been related in oncogenesis." (PMID 31551474, 2019). "In contrast several lines of evidence provide insights into potential mechanism by which cdk10 act like a putative new tumor suppressor gene in multiple types of human cancers." (PMID 31413335, 2019). "SLC4A4 mRNA expression depends exclusively on hypoxia inducible factor 1 subunit alpha, a tumor suppressor gene in ccRCC." (PMID 30668544, 2019). "Tet methylcytosine dioxygenase 2 (TET2) is a tumor suppressor gene that is inactivated in a wide range of hematological cancers." (PMID 31231651, 2019). "PTEN acts as a tumor suppressor gene through inhibition of the PI3K/AKT signaling pathway, which participates in the regulation of various biological functions, including cellular growth, metabolism and survival." (PMID 31469661, 2019). "Although GLS2 has been suggested to act as a tumor suppressor gene, nothing is known about its role in S. aureus infection." (PMID 30289878, 2018). "S100A2 has been identified as a markedly downregulated gene in tumor-derived mammary epithelial cell lines and was assumed as a tumor suppressor gene." (PMID 30558666, 2018). "In past decades, studies revealed that PARK2 was a vital tumor suppressor gene in many malignant solid tumors." (PMID 29515107, 2018). "In summary, this study reports that miR-29c was frequently downregulated in NSCLC and acts as a tumor suppressor gene in NSCLC cells by negatively regulating AKT2." (PMID 29789623, 2018). "Several studies have suggested possible roles of GSK-3β as a tumor suppressor gene in HCC, whereas, other studies have indicated that GSK-3β is a potential therapeutic target for this cancer." (PMID 29445085, 2018). "The Bax gene is a tumor suppressor gene, and Bcl-2 is an antiapoptotic gene that antagonizes the function of Bax." (PMID 29636773, 2018). "Based on these reports, it seems that miR-511 displays contrasting roles in different tumor types, implying that the cancer type determines the role of miR-511 as an oncogene or tumor suppressor gene." (PMID 28114950, 2017). "PSP94 is a suppressor of tumor growth and metastasis; SLIT2 inhibits prostate cancer cell proliferation and invasion; and CDKN2A is a critical tumor suppressor gene." (PMID 28410242, 2017). "PR domain zinc finger protein 5 (PRDM5), a member of the Kruppel-like zinc finger family is an important tumour suppressor gene and has been found to be methylated in gastric human carcinomas like." (PMID 28144288, 2017). "Checkpoint with Forkhead-associated and Ring finger domains (CHFR) is a G2/M checkpoint and tumor-suppressor gene." (PMID 29312643, 2017). "Depending on tumor type and disease stage, as well as therapy, BCL2 seems to be able to act as both an oncogene and a tumor suppressor gene." (PMID 28396899, 2017).
tumor (continued). "CTCF is a haploinsufficient tumour suppressor gene with diverse normal functions in genome structure and gene regulation." (PMID 28319062, 2017). "This expression pattern of these two IQGAP isoforms across different cancer types supports the notion that IQGAP2 possibly plays the role of a tumor suppressor gene whereas IQGAP3 is more likely to be an oncogene." (PMID 29073199, 2017). "CDH5 is a non-histone chromosomal protein belonging to the SWI2/SNF2-related superfamily of ATPases and a potent tumour suppressor gene." (PMID 28144288, 2017). "miR-184 in human cancer appears to be context-dependent with roles as an oncogene and a tumour suppressor gene." (PMID 28736583, 2017). "Altogether, these results demonstrate a role for SLC7A11-AS1 in cell proliferation and cell cycle progression and as a tumor suppressor gene." (PMID 29348845, 2017). "It has been shown that POU2F1 acts not only as an oncogene but also as a tumor suppressor gene in different cancers." (PMID 28489585, 2017). "It has been reported that miR-195-5p is a tumor-suppressor gene that mainly suppresses cell proliferation and invasion and is down regulated in cancer patients." (PMID 28498798, 2017). "We observed a distinct increase of SLC6A3 mRNA (>200-fold) in ccRCC tissue compared to the normal parenchyma indicating a role as tumor suppressor gene." (PMID 26831905, 2016). "The lncRNA growth arrest special 5 (GAS5), was previously identified to be down-regulated and functions as a tumor suppressor gene in many kinds of cancers." (PMID 27863421, 2016). "In conclusion, our study indicates that miR-381 functions as an oncogene, and LRRC4 serves as a tumour suppressor gene in OS." (PMID 27612424, 2016). "Among the top 15 predicted targets (ordered by increasing mirSVR score), VSNL1 is a known tumor-suppressor gene regulating cell migration in several cancer types." (PMID 26683098, 2016). "BECN1, an autophagy initiation gene also involved in ploidy homeostasis, increases tumor formation when monoallelically deleted." (PMID 27391266, 2016). "This gene has been extensively studied in the past decade and has been characterized as an apoptosis-inducer and tumor-suppressor gene." (PMID 27124579, 2016). "The findings presented here reinforce the role of TAp73 as tumor suppressor gene and indicate that the regulation of cellular metabolism by TAp73 contributes to its tumor suppressor function." (PMID 27119504, 2016). "We found that another solute carrier gene, SLC17A7, is also a candidate bivalent tumor suppressor gene." (PMID 25749033, 2015). "In fact, the identifying Beclin-1 as a tumor suppressor gene in human cancer provided early evidence for the tumor suppressive role of autophagy." (PMID 26561802, 2015). "An increasing body of evidence shows that PTEN functions as a tumour suppressor gene in some tissues, and its tumour suppressor activity is dependent on its lipid phosphatase activity, which negatively regulates the PI3K-AKT-mTOR pathway." (PMID 26511107, 2015). "Epigenetic inactivation of GATA4 by promoter hypermethylation was observed in both AML cell lines and pediatric AML samples; our study implicates GATA4 as a putative tumor suppressor gene in pediatric AML." (PMID 26490736, 2015). "Our data shows that miR-216b, acting as a tumor suppressor gene, inhibits cell proliferation, colony formation and induces G0/G1 cell cycle arrest, whereas, UCA1 can overturn these inhibitory effects of miR-216b on HCC cells." (PMID 25760077, 2015). "MiR-342 has also been shown to act as a tumor suppressor gene in CRC development by regulating aberrant DNA hypermethylation." (PMID 26569605, 2015).
tumor (continued). "This gene regulates neuronal and muscle differentiation and is a tumor suppressor gene in several types of cancer." (PMID 26112950, 2015). "The role of miR-100 in cancer is quite contradictory, since it can behave either as an oncogene or as a tumor suppressor gene, depending on the tumor type." (PMID 25537513, 2015). "In contrast, mammary gland tumorigenesis was enhanced in Apc1638NCtnnb1+/- mice, perhaps because Ctnnb1 functions as a tumor suppressor gene in the mammary gland tumors via β-catenin’s role in E-cadherin-dependent tumor suppression." (PMID 26528816, 2015). "The present study demonstrate that up-regulator of cell proliferation (URGCP), a recently identified tumor-promoting gene found in several tumor types, is markedly overexpressed in human NSCLC cell lines and clinical NSCLC samples." (PMID 26429875, 2015). "The results suggested that miR-302b acted as a tumor suppressor gene in ESCC by inhibiting proliferation, inducing apoptosis, and repressing invasion." (PMID 24438167, 2014). "The CIS RPS6KA5 was deleted in approximately 25% of GBMs and was also found in the top 7% of genes down-regulated at the mRNA level in the microarray dataset, implicating it as a candidate tumor suppressor gene." (PMID 25423036, 2014). "RECK is thought to be a tumor invasion and metastasis suppressor gene, and was also found to inhibit tumor cell growth and motility in both lung and bladder cancer." (PMID 25084400, 2014). "The expression of OGN was absent in several cancer cell lines, implicating its potential role as a tumor suppressor gene in cancer biology, although its physiological function has not been fully elucidated." (PMID 24587265, 2014). "On the other side, miR-17-92 cluster also can negatively regulate the oncogene E2F1 or MYC to inhibit cell cycle progression as the tumor suppressor gene." (PMID 24722426, 2014). "N-myc downstream-regulated gene 2 (NDRG2), a novel tumour suppressor and cell stress-related gene, is involved in many cell metabolic processes, such as hormone, ion and fluid metabolism." (PMID 24636131, 2014). "HES1 has been suggested to have both oncogenic and tumor suppressive functions, whereas KLF10 has been suggested to be a tumor suppressor gene." (PMID 24885297, 2014). "These two previous instances, and the computational and experimental effort detailed here, establish AGTR1 as a potential tumor suppressor gene in HNSCC." (PMID 25186767, 2014). "Recently, SMG1 was suggested as a novel potential tumor suppressor gene, particularly in hypoxic tumors." (PMID 25257528, 2014). "BRG1 gene is frequently deleted or mutated in a variety of tumor cell lines, implicating BRG1 as a potential tumor suppressor gene, and mouse models have confirmed the tumor suppressor activities of BRG1." (PMID 25157878, 2014). "The tumor suppressor gene and epithelial cell marker E-cadherin (Cdh1) was markedly up-regulated and the oncogenic transcription factor Myc was down-regulated by Tcf7l2 silencing." (PMID 25414334, 2014). "In the past research, NDRG2 was shown as a tumor suppressor gene in many kinds of tumors, which promoted differentiation and apoptosis and inhibited proliferation in a variety of tumors." (PMID 23307246, 2013). "The mechanism of the Notch receptor function as an oncogene or tumor suppressor gene remains to be elucidated." (PMID 23599800, 2013). "Our study indicates for the first time that, in addition to its role in brain development, MCPH1 also functions as a tumor suppressor gene and is regulated by miR-27a." (PMID 23472065, 2013). "A loss of function of DLEC1 was previously related with several cancers, suggesting that DLEC1 acts as a tumor suppressor gene." (PMID 24222856, 2013).